HSP90B1 (heat shock protein 90 beta family member 1)
Diseases named in the same sentence as HSP90B1 in open-access papers (continued):
Sharing a sentence is not in itself a finding about the gene and the disease.
clear cell kidney carcinomas (2 papers, 2015 to 2024). "We first analyzed the expression levels of HSP90B1 in clear cell renal cell carcinoma (ccRCC) using bioinformatics approaches." (PMID 39149033, 2024).
endometriosis (2 papers, 2020 to 2021). The growth of functional endometrial tissue in anatomic sites outside the uterine body. "The endothelial cell-related gene HSP90B1 was only elevated in PE, MSE, and stage I–II endometriosis." (PMID 35069565, 2021).
Hepatic steatosis (2 papers, 2021 to 2025). Steatosis is a term used to denote lipid accumulation within hepatocytes. "HSP90B1 is an essential immune chaperone to regulate both innate and adaptive immunity and has previously been shown to be increased in a zebrafish model of hepatic steatosis induced by high-fat and high-cholesterol diet." (PMID 34685777, 2021).
lung squamous cell carcinoma (2 papers, 2011 to 2021). "Mesothelioma and squamous cell lung cancer cells express higher levels of HSP90B1 mRNA than matched normal controls." (PMID 21489244, 2011).
psoriasis (2 papers, 2013 to 2025). An autoimmune condition characterized by red, well-delineated plaques with silvery scales that are usually on the extensor surfaces and scalp. "HSP90B1 and CANX were significantly increased in psoriasis as clinical control compared with the normal control." (PMID 39938773, 2025).
pulmonary fibrosis (2 papers, 2023 to 2025). Chronic progressive interstitial lung disorder characterized by the replacement of the lung tissue by connective tissue, leading to progressive dyspnea, respiratory failure, or right heart failure. "Remarkably, hucMSC-EV intervention effectively suppressed the expression of Hsp90b1 both in vivo and in vitro, indicating the involvement of Hsp90b1 in the mechanism underlying the inhibition of silica-induced pulmonary fibrosis by hucMSC-EVs." (PMID 37833927, 2023). "Taken together, these results suggest that hucMSC-EVs exert their inhibitory effects on fibroblast collagen synthesis and secretion and silica-induced pulmonary fibrosis in mice through the targeted delivery of miR-148a-3p, which downregulates Hsp90b1." (PMID 37833927, 2023). "To determine the specific effect of Hsp90b1 in silica-induced pulmonary fibrosis, we designed three small interfering RNAs (siRNAs) (siHsp90b1-1129/1471/1671) targeting Hsp90b1 and assessed their efficacy." (PMID 37833927, 2023). "We subsequently sought to determine whether Hsp90b1 was correlated with the inhibition of pulmonary fibrosis by hucMSC-EVs." (PMID 37833927, 2023).
thyroid cancer (2 papers, 2022 to 2024). "HSP90B1 can also affect the progression of thyroid cancer by regulating the expression and sub-localization of its client protein ITGA2." (PMID 36291587, 2022).
tuberculosis (2 papers, 2018 to 2022). A chronic, recurrent infection caused by the bacterium Mycobacterium tuberculosis. "We hypothesized that human HSP90B1 regulates monocyte and T-cell responses to Mycobacterium tuberculosis (Mtb) and bacilli Calmette-Guerin (BCG) and that its variants are associated with susceptibility to TB disease." (PMID 30550567, 2018).
adenomyosis (1 paper, 2020). The growth of endometrial tissue inside the muscular wall of the uterine corpus. "Therefore, STAT3, VIM, VEGFA and HSP90B1 that were also annotated in interleukin-4 and interleukin-13 signalling in the present GSEA need to be validated to verify potential downregulation of this pathway in women with adenomyosis." (PMID 32933042, 2020).
chronic kidney disease (1 paper, 2022). Impairment of the renal function secondary to chronic kidney damage persisting for three or more months. "Moreover, a system biology analysis of the protein–protein interaction (PPI) with SARS-CoV-2 indicated ten hub proteins, including HSP90B1, which may be therapeutic targets in COVID-19 patients with CKD (chronic kidney disease) comorbidity." (PMID 35677655, 2022).
chronic myeloid leukemia (1 paper, 2025). "HSP90B1 is directly regulated by miR‐223, a mechanism that affects the progression of diseases such as chronic myeloid leukemia." (PMID 40371728, 2025).
co-infection (1 paper, 2014). "maxima co-infection compared with uninfected controls (ANXA1, HSP90B1, VEGFA, MTTP, TNFSF11B, TCF12, APP, and CXCL14)." (PMID 25504150, 2014).
dementia (1 paper, 2020). Loss of intellectual abilities interfering with an individual's social and occupational functions. "ACSL4, ECHS1, and HSP90B1 have no reported association with AD or related dementias, however, which suggests that our study has the potential to identify new targets in the molecular pathogenesis of this disease." (PMID 33116184, 2020).
dystrophin deficiency (1 paper, 2023). "Likewise, HSP90B1, a molecular chaperone involved in quality control, protein folding, calcium homeostasis, and ERAD, was upregulated by dystrophin deficiency." (PMID 37179835, 2023).
epilepsy (1 paper, 2020). A brain disorder characterized by episodes of abnormally increased neuronal discharge resulting in transient episodes of sensory or motor neurological dysfunction, or psychic dysfunction. "Heat shock protein 90 kDa beta member 1(HSP90B1), a member of the Hsp90 family, showed decrease expression in the plasma of patients with epilepsy." (PMID 33082886, 2020).
Globozoospermia (1 paper, 2024). Any structural anomaly of the acrosome resulting in a round sperm head. "Heat shock protein 90B1 (HSP90B1) is an ER molecular chaperone that has been shown to be a testis-specific protein, and HSP90B1 deficiency leads to a globozoospermia-syndrome like phenotype." (PMID 39269275, 2024).
head and neck squamous cell carcinoma (1 paper, 2024). A squamous cell carcinoma that arises from any of the following anatomic sites: lip and oral cavity, nasal cavity, paranasal sinuses, pharynx, larynx, and salivary glands. "To elucidate the role of HSP90B1 in head and neck squamous cell carcinoma, we conducted knockdown and overexpression experiments on TU686 and SAS cell lines." (PMID 38590708, 2024). "To further understand the in vivo functional role of HSP90B1 in head and neck squamous cell carcinoma (HNSC), we generated a cell line with stable HSP90B1 knockdown (shHSP90B1) and a control cell line (shNC)." (PMID 38590708, 2024). "However, the specific role and underlying mechanisms of heat shock protein 90 beta family member 1 (HSP90B1) in modulating autophagy within head and neck squamous cell carcinoma (HNSCC) remain elusive." (PMID 38590708, 2024). "Furthermore, PCR analysis of cell lines revealed pronounced upregulation of HSP90B1 in head and neck squamous cell carcinoma (HNSC) cells (TU686 and Fadu, SAS) when contrasted with normal human oral keratinocytes (HOK)." (PMID 38590708, 2024).
human papillomavirus infection (1 paper, 2024). "The analysis revealed significant enrichment of HSP90B1 such as focal adhesion, human papillomavirus infection, the PI3K/AKT signaling pathway, and ECM-receptor interactions." (PMID 38590708, 2024).
keloid (1 paper, 2021). An irregularly shaped, elevated mark on the skin caused by deposits of excessive amounts of collagen during wound healing. "However, the pathological mechanism of ITGB2 and HSP90B1 in keloid formation is still unknown." (PMID 35082796, 2021).
legionellosis (1 paper, 2016). Any disease caused by Legionella bacteria. "Our major finding pathways- based network analysis between the patients and a normal one, include antigen processing and presentation (HSPA5, HSPA8), protein processing in the endoplasmic reticulum (HSP90B1, HSPA5, HSPA8) and legionellosis (HSPA8)." (PMID 27895852, 2016).
mantle cell lymphoma (1 paper, 2022). Mantle cell lymphoma is a rare form of malignant non-Hodgkin lymphoma affecting B lymphocytes in the lymph nodes in a region called the ``mantle zone''. "HSP90B1 (GRP94), HSP70, ATF6, and DDIT3 were all upregulated after verapamil and bortezomib treatment in mantle cell lymphoma." (PMID 36435779, 2022).
osteoporosis (1 paper, 2022). A condition of reduced bone mass, with decreased cortical thickness and a decrease in the number and size of the trabeculae of cancellous bone (but normal chemical composition), resulting in increased fracture incidence. "According to previous study, EIF5B and HSP90B1 have also not been reported in osteoporosis." (PMID 35859791, 2022).
pemphigoid (1 paper, 2021). "Thus, the discovery of significant upregulation of Hsp90 genes HSP90B1, HSP90B2P, HSP90B3P in laminin-332 pemphigoid IgG treated may present a possible therapeutic approach." (PMID 34899732, 2021).
prostate (1 paper, 2021). "HSP90B1 is a molecular chaperone protein in which its downregulation is associated with prostate carcinogenesis and metastasis." (PMID 34366863, 2021).
renal carcinoma (1 paper, 2024). A carcinoma arising from the epithelium of the renal parenchyma or the renal pelvis. "To enhance the credibility of our bioinformatics analysis, we validated the expression of HSP90B1 in both ccRCC tissues and renal cancer cells." (PMID 39149033, 2024). "RT-PCR analysis confirmed the increased expression of HSP90B1 in renal cancer cells and ccRCC tissues." (PMID 39149033, 2024).
silicosis (1 paper, 2023). Silicosis is a respiratory disease caused by breathing in (inhaling) silica dust. "Collectively, our findings provide compelling evidence that links miR-148a-3p present in hucMSC-EVs with the amelioration of silicosis, suggesting its therapeutic potential by specifically targeting Hsp90b1, thereby inhibiting fibroblast collagen activities." (PMID 37833927, 2023).
Spinocerebellar Ataxia 17 (1 paper, 2023). "An ENCODE analysis exhibited SP2 (Sp2 transcription factor), as the top functional element related to HSP90B1, whereas DisGeNET showed Spinocerebellar Ataxia 17 as one of the top related diseases associated with it." (PMID 36766730, 2023).
tumor (201 papers, 2004 to 2026). "The involvement of HSP90B1 in immune cell infiltration, particularly its association with cancer-associated fibroblasts, underscores its broader influence on the tumor microenvironment." (PMID 41009692, 2025). "Elevated HSP90B1 expression is clinically associated with advanced tumor stages and reduced survival, highlighting its role in promoting aggressive ccRCC phenotypes." (PMID 41009692, 2025). "Using mice with KO of tamoxifen-inducible, Treg-specific Hsp90b1 (encoding gp96), we discovered that gp96 was required for Treg infiltration into the tumor." (PMID 38787791, 2024). "Beyond its response to heat stress, HSP90B1 plays a significant part in adapting to diverse tumor microenvironmental factors such as glucose deficiency, hypoxia, acidosis, and immune stimulation." (PMID 38590708, 2024). "HSP90B1 expression was positively correlated with microsatellite instability and tumor mutational burden." (PMID 38243263, 2024). "In summary, we performed a comprehensive evaluation of HSP90B1 in cancer, which revealed its underlying role as a prognostic indicator for patients and its role in the regulation of tumor development, metabolism and immune microenvironment." (PMID 38243263, 2024). "Subsequently, HSP90B1 expression and the immune invasion of cancer-associated fibroblasts in various tumours were analysed." (PMID 36291587, 2022). "And, the low expression of HSP90B1 may inhibit antigen release of cancer cell, which causes immune cells failing to recognize tumor cells." (PMID 36765073, 2023). "However, little is known about the molecular mechanisms underlying HSP90B1-induced resistance to radiotherapy in GBM tumor cells." (PMID 37750323, 2023). "Thus, rs2307842 influenced HSP90B1 overexpression only in the tumor fraction of the CLL patients with the polymorphism." (PMID 25880332, 2015). "Additionally, a statistical correlation was observed between the expression of HSP90B1 and cancer-related fibroblast infiltration, tumour mutation burden, and protein phosphorylation, which validated the role of HSP90B1 in tumorigenesis from various perspectives." (PMID 36291587, 2022). "These analyses revealeda significant upregulation of ER chaperone mRNA expression in aHGGrelative to aLGG and aNNB that was associated with tumor aggressiveness and patientsurvival for HSPA5, HSP90B1, P4HB, and SERPINH1." (PMID 41287960, 2026). "Immunohistochemical data confirm cytoplasmic overexpression of HSP90B1 in bladder tumors, reinforcing its functional involvement in tumor pathophysiology." (PMID 41009692, 2025). "Inhibition of hsp90b1 leads to a significant reduction in tumor cell proliferation and the ability to metastasize." (PMID 41155202, 2025). "During oncogenesis, tumor cells exhibit an increased reliance on HSPs (including HSP90B1) for chaperoning to support their proliferation due to the misfolding of oncoproteins requiring enhanced chaperone activity for correct folding." (PMID 38665430, 2024). "Numerous studies have underscored HSP90B1 as a potent molecular adjuvant, functioning as a carrier for tumor antigenic peptides and playing a crucial role in tumor antigen presentation and activation of CD8 + T lymphocytes." (PMID 38243263, 2024). "Subsequently, we analyzed the following relationships between HSP90B1 expression and tumor mutational burden (TMB) in various tumors, revealing a positive correlation between HSP90B1 expression and TMB." (PMID 38243263, 2024). "Conversely, in LUAD, PRAD, STAD, THCA, and UCEC, HSP90B1 expression exhibited a positive correlation with tumor purity (all p < 0.05)." (PMID 38243263, 2024). "The single-cell RNA sequencing analysis further highlighted that HSP90B1 was significantly higher in tumor cells compared to surrounding cells, revealing a potential target therapeutic window." (PMID 38243263, 2024).
tumor (continued). "HSP90b1 has been identified as a potential molecular carrier for tumor antigens, aiding in tumor antigen presentation and activating CD8 + cytotoxic T lymphocytes, which are crucial for anti-tumor specific immune responses." (PMID 39048939, 2024). "HSP90B1 expression was also discovered to be positively correlated with tumor metabolism, cell cycle-related pathways and the expression of immune checkpoint genes." (PMID 38243263, 2024). "Collectively, FKC inhibits glucose metabolism and tumor angiogenesis in NPC by targeting the HSP90B1/EGFR/PI3K/Akt/mTOR signaling axis." (PMID 38711062, 2024). "HSP90B1 influences tumor progression through various pathways, and elucidating its specific mechanisms in HNSC warrants additional investigation." (PMID 38590708, 2024). "The HSP90B1 elevation is often accompanied by alterations in key molecules involved in tumor cell proliferation, invasion and apoptosis, indicating that HSP90B1 has a significant impact on cancer progression and resistance to treatment." (PMID 37750323, 2023). "Our findings reveal that tumor cells in relapsed patient exhibit higher expression levels of HSP90B1 and HSPA5, and demonstrate significantly enriched pathways regarding endoplasmic reticulum stress and unfolded protein response." (PMID 38035111, 2023). "Under ER stress many proteins including HSPA5, HSP90B1/GRP94, ER-associated degradation, PDI (protein disulfide isomerase), ATF6, ERN1, XBP1, EIF2AK3 and EIF2A are overexpressed in many forms of tumor cells." (PMID 36497321, 2022). "Then, GO enrichment analysis further indicates the mechanism of HSP90B1 regulating tumour progression." (PMID 36291587, 2022). "A comparison was made between the phosphorylation of HSP90B1 in normal and primary tumour tissues, and putative functional mechanisms in HSP90B1-mediated oncogenesis were investigated." (PMID 36291587, 2022). "On examining the levels of HSP90B1 expression in each tumour, it was observed to be highly expressed in the majority of cancers." (PMID 36291587, 2022). "The variations in HSP90B1 expression levels observed across the spectrum of tumour types are indicative of its diverse processes and functions." (PMID 36291587, 2022). "According to the expression difference of HSP90B1 RNA in tumours and corresponding normal tissues, the tumour type with the most significant difference was selected for immunohistochemistry (IHC) analysis." (PMID 36291587, 2022). "In the TCGA tumours of HNSC, HNSC-HPV(-), and THYM, a statistically positive association between the estimated infiltration value of cancer-associated fibroblasts and HSP90B1 expression was observed." (PMID 36291587, 2022). "The expression of HSP90B1 protein in these tumour tissues was observed to be significantly higher than that in normal tissues (p < 0.01)." (PMID 36291587, 2022). "The overexpression of HSP90B1 on the cell membrane has been reported to boost cell proliferation and tumour development by increasing HER2 dimerization and the downstream signalling cascade." (PMID 36291587, 2022). "HSP90B1 downregulation mediated the PI3K/AKT/mTOR pathway to inhibit tumor growth in vitro and in vivo." (PMID 36452480, 2022). "In BRAC tissues, the expression of HSP90AA1, HSP90AB1, and HSP90B1 was conformably correlated with the expression of biomarkers of some lineages of CD4+ helper T (Th) cells and tumor-associated macrophages (TAMs)." (PMID 33145341, 2020). "Their study showed that tumour-derived GP96 (HSP90B1) and HSP70 preparations were able to eradicate established tumours in animal models." (PMID 29702669, 2018). "Three members of the HSP90 gene family (HSP90AA1, HSP90AB1, and HSP90B1) analyzed were all down-regulated following OCT4B1 suppression in all three tumor cell lines except for HSP90B1 in AGS cells that showed less than 2-fold up-regulation." (PMID 26862520, 2016).